ENSG00000264813 (novel protein)
Gene: Protein-coding gene on chromosome 17 (63,484,823 to 63,521,848, forward strand). Ensembl gene ENSG00000264813.
Genetic constraint (gnomAD): Missense variants: 835 observed, 883.39 expected, observed/expected ratio (o/e) 0.95, 90% interval 0.89 to 1. Synonymous variants: 355 observed, 356.8 expected, observed/expected ratio (o/e) 0.99, 90% interval 0.91 to 1.09.